ALKBH1 (alkB homolog 1, histone H2A dioxygenase)
Description:
Dioxygenase that acts on nucleic acids, such as DNA and tRNA. Requires molecular oxygen, alpha-ketoglutarate and iron. A number of activities have been described for this dioxygenase, but recent results suggest that it mainly acts on tRNAs and mediates their demethylation or oxidation depending on the context and subcellular compartment. Mainly acts as a tRNA demethylase by removing N(1)-methyladenine from various tRNAs, with a preference for N(1)-methyladenine at position 58 (m1A58) present on a stem loop structure of tRNAs. Acts as a regulator of translation initiation and elongation in response to glucose deprivation: regulates both translation initiation, by mediating demethylation of tRNA(Met), and translation elongation, N(1)- methyladenine-containing tRNAs being preferentially recruited to polysomes to promote translation elongation. In mitochondrion, specifically interacts with mt-tRNA(Met) and mediates oxidation of mt-tRNA(Met) methylated at cytosine(34) to form 5-formylcytosine (f(5)c) at this position. mt-tRNA(Met) containing the f(5)c modification at the wobble position enables recognition of the AUA codon in addition to the AUG codon, expanding codon recognition in mitochondrial translation. Specifically demethylates DNA methylated on the 6th position of adenine (N(6)-methyladenosine) DNA. N(6)- methyladenosine (m6A) DNA is present at some L1 elements in embryonic stem cells and probably promotes their silencing (By similarity). Demethylates mRNAs containing N(3)-methylcytidine modification. Also able to repair alkylated single-stranded DNA by oxidative demethylation, but with low activity. Also has DNA lyase activity and introduces double-stranded breaks at abasic sites: cleaves both single-stranded DNA and double-stranded DNA at abasic sites, with the greatest activity towards double-stranded DNA with two abasic sites. DNA lyase activity does not require alpha-ketoglutarate and iron and leads to the formation of an irreversible covalent protein-DNA adduct with the 5' DNA product. DNA lyase activity is not required during base excision repair and class switch recombination of the immunoglobulin heavy chain during B lymphocyte activation. May play a role in placental trophoblast lineage differentiation (By similarity).
Synonyms: ABH; ABH1; ALKBH; hABH; alkB
Tractability: Small molecule: a structure with a bound ligand is known. PROTAC: ubiquitination databases record sites on it; its protein half-life has been measured.
Target class: Enzyme; Oxidoreductase
Gene: Protein-coding gene on chromosome 14 (77,672,404 to 77,708,023, reverse strand). Ensembl gene ENSG00000100601.
Subcellular location: Nucleus; Mitochondrion
Subcellular location (Human Protein Atlas): Nucleoplasm; Endoplasmic reticulum
Gene Ontology:
Molecular function: 2-oxoglutarate-dependent tRNA 5-methylcytidine formyltransferase activity; broad specificity oxidative DNA demethylase activity; class I DNA-(apurinic or apyrimidinic site) endonuclease activity; DNA N6-methyladenine demethylase activity; ferrous iron binding; oxidative RNA demethylase activity; tRNA binding; tRNA demethylase activity; chemoattractant activity
Biological process: DNA repair; oxidative RNA demethylation; positive regulation of gene expression, epigenetic; regulation of mitochondrial translation; regulation of translational elongation; regulation of translational initiation; regulation of translational initiation by tRNA modification; tRNA wobble cytosine modification; positive chemotaxis
Cellular component: mitochondrion; nucleoplasm; nucleus; mitochondrial matrix; euchromatin
Genetic constraint (gnomAD): Loss-of-function variants: 27 observed, 33.01 expected, observed/expected ratio (o/e) 0.82, 90% interval 0.6 to 1.13. The upper end of that interval is the gene's LOEUF score, 1.13, which puts it in group 4 of 6, group 1 being the genes least tolerant of losing a copy. Missense variants: 486 observed, 512.3 expected, observed/expected ratio (o/e) 0.95, 90% interval 0.88 to 1.02. Synonymous variants: 182 observed, 195.35 expected, observed/expected ratio (o/e) 0.93, 90% interval 0.82 to 1.05.
Homologues: Orthologues: chimpanzee ALKBH1 (99% identical), macaque ALKBH1 (96% identical), pig ALKBH1 (89% identical), dog ALKBH1 (87% identical), guinea pig ALKBH1 (86% identical), rabbit ALKBH1 (86% identical), mouse Alkbh1 (83% identical), rat Alkbh1 (82% identical), zebrafish alkbh1 (50% identical), tropical clawed frog alkbh1 (38% identical), Drosophila melanogaster AlkB (30% identical), Caenorhabditis elegans alkb-1 (26% identical).
Diseases named in the same sentence as ALKBH1 in open-access papers:
ALKBH1 is named in the same sentence as 44 diseases in open-access papers, as found by Europe PMC text mining. Sharing a sentence is not in itself a finding about the gene and the disease. The quoted sentences say what the papers report.
glioblastoma (17 papers, 2017 to 2025). The most malignant astrocytic tumor (WHO grade IV). "For example, ALKBH1, which has been implicated in gastric cancer and glioblastoma, has the potential to induce mitochondrial damage by targeting N6-methyladenine (N6mA) in DNA and exerting its demethylase activity, thereby downregulating and disrupting genes encoded by mitochondrial DNA." (PMID 40646842, 2025). "Although hypoxia-response genes such as MIAT might be the target genes of ALKBH1-related m6A modification in glioblastoma, the profiling of m6A and the underlying mechanism of MIAT regulation by m6A during AS development is unknown." (PMID 31797919, 2019). "In glioblastoma, ALKBH1 dynamically regulates the m6A level of DNA, and its depletion leads to transcriptional silencing of oncogenic pathways by decreasing chromatin accessibility." (PMID 41017026, 2025). "In human glioblastoma, ALKBH1 has been reported to induce 6 mA demethylation, silencing tumor suppressor genes and activating downstream hypoxic response elements." (PMID 40867005, 2025). "Conversely, ALKBH1 is overexpressed in lung cancer, gastric cancer, glioblastoma and colorectal cancer and its overexpression markedly enhances viability and migration." (PMID 41017026, 2025). "In a patient-derived human glioblastoma model, the deliberate reduction of ALKBH1 expression through targeted knockdown proved to be highly effective." (PMID 38317214, 2024). "For instance, in glioblastoma, the DNA demethylase ALKBH1 regulates N6‐mA levels dynamically, and its depletion leads to transcriptional silencing of oncogenic pathways by decreasing chromatin accessibility." (PMID 36550779, 2023). "Several studies on the roles of ALKBH1 in cancer as a genomic DNA N6mA demethylase, such as glioblastoma, TSCC, HCC, and GC." (PMID 37007161, 2023). "Targeted knockdown of ALKBH1 in a patient-derived human glioblastoma model inhibited the proliferation of tumor cells, which in turn prolonged the survival of mice." (PMID 37007161, 2023). "Collectively, N6AMT1-mediated 6mA modification inhibits stomach and liver tumorigenesis and metastasis, while ALKBH1 maintains glioblastoma tumor cell viability and stemness properties via 6mA demethylation." (PMID 35256595, 2022). "The lncRNA myocardial infarction-associated transcript (MIAT), as a hypoxia-response gene, was reported as a target gene of ALKBH1-modulated m6A in glioblastoma." (PMID 31797919, 2019). "Therefore, we knocked down ALKBH1 using siRNAs in four glioblastoma cell lines accompanying with [15N5]-dA treatment." (PMID 35501312, 2022). "In addition, the demethylation effect of ALKBH1 was also reported in glioblastoma." (PMID 35812743, 2022). "Furthermore, we identified ALKBH1 as a demethylase and dynamic regulator of 6mA in glioblastoma." (PMID 32296573, 2020). "Furthermore, two research groups have demonstrated that ALKBH1 and ALKBH5 are related to glioblastoma." (PMID 33744868, 2021). "In glioblastoma (GBM), NSUN2, DNMT3B, NSUN5, TRDMT1, ALKBH1, and HNRNPC were selected." (PMID 40565233, 2025). "However, the specific mechanism of action of the ALKBH1 gene has not been clearly reported, but it is a potential therapeutic target for a variety of cancers, such as gastric cancer, liver cancer, glioblastoma, and head and neck cancer." (PMID 33779693, 2021).
gastric cancer (13 papers, 2020 to 2025). A primary or metastatic malignant neoplasm involving the stomach. "Elevated expression of ALKBH1 has been implicated in promoting several types of tumors, including gastric cancer, lung cancer and head and neck squamous cell carcinoma." (PMID 40867005, 2025). "Concurrently, reports have emerged delineating the associations of SNPs in ALKBH1 with the risk of developing gastric cancer and acute lymphoblastic." (PMID 41017026, 2025). "Overall, the results suggest that these drugs have the potential to be used as anticancer agents targeting ALKBH1 to regulate gastric cancer cell growth." (PMID 38317214, 2024). "The magnified image clearly shows a large amount of ALKBH1 in gastric cancer tissues, with advanced tumors showing a large amount of red color, resulting in some tissues appearing yellow." (PMID 38317214, 2024). "Pharmacogenomic analysis of gastric cancer cell lines further indicated that ALKBH1 inactivation correlated with heightened sensitivity to specific small-molecule drugs." (PMID 38317214, 2024). "The data revealed that the expression of ALKBH1 was consistently higher than the other two gastric cancer biomarkers, AQP1 and PECAM1, across all 10 clusters." (PMID 38317214, 2024). "In gastric cancer, ALKBH1 is overexpressed, and its overexpression markedly enhances viability and migration." (PMID 36550779, 2023). "Moreover, overexpression of ALKBH1 reversed the inhibitory effect of miRNA-339-5p, an upstream gene of ALKBH1, on the proliferation and migration ability of gastric cancer (GC)." (PMID 37007161, 2023). "Low expression of miR-339-5p has also been documented to be closely related to metastasis and prognosis of gastric cancer, and miR-339-5p can inhibit the malignant development of GC by negatively regulating ALKBH1." (PMID 35093110, 2022). "We found that in 10 pairs of human gastric cancer and normal tissues, ALKBH1, ALKBH4, ALKBH8, and FTO were highly expressed in the gastric cancer tissues." (PMID 38902235, 2024). "In the context of gastric cancer, the expression of demethylase genes, FTO and ALKBH1, holds prognostic significance, possibly indicating their involvement in autophagy regulation." (PMID 38148841, 2023).
lung carcinoma (8 papers, 2020 to 2025). "In lung cancer, ALKBH1's elevated expression was linked to enhanced invasion and migration of cancer cells in vitro, while its silencing significantly curtailed these abilities." (PMID 38317214, 2024). "In lung cancer, ALKBH1 regulates the m6A modification of mRNA, promoting lung cancer cell invasion and migration." (PMID 41017026, 2025). "In both lung cancer tissues and cultured cells, there was an observed upregulation in the expression of ALKBH1." (PMID 38317214, 2024). "Silencing ALKBH1 in these lung cancer cells led to a significant inhibition of their in vitro invasion and migration capabilities." (PMID 38317214, 2024). "ALKBH1 is upregulated in lung cancer tissues and cells, and silencing of ALKBH1 significantly inhibits the invasion and migration ability of lung cancer cells in vitro." (PMID 37007161, 2023).
Obesity (8 papers, 2011 to 2024). Accumulation of substantial excess body fat. "There are nine AlkB homologs including ALKBH1–8 and fat mass and obesity-associated (FTO) with low sequence identity in humans." (PMID 38255759, 2024). "The human ALKBH family consists of nine proteins (ALKBH1–8 and fat mass and obesity associated [FTO]) that catalyze the demethylation of various RNA as well as DNA and proteins." (PMID 38550277, 2024). "Nine AlkB members are identified in the human genome, including ALKBH1-8 and FTO (fat mass and obesity-associated protein)." (PMID 37620312, 2023). "Mammals have nine different ALKBH family members: ALKBH1 to ALKBH8 and the fat mass and obesity-associated (FTO) protein." (PMID 32933187, 2020). "There are 9 known homologues of AlkB in humans including ALKBH1 through ALKBH8 and FTO, the fat mass and obesity-associated protein." (PMID 28231280, 2017).
glioma (7 papers, 2018 to 2025). A benign or malignant brain and spinal cord tumor that arises from glial cells (astrocytes, oligodendrocytes, ependymal cells). "It is also possible that the post-replicative and epigenetic 6mA was erased by the proposed demethylase candidate ALKBH1 in glioma." (PMID 35501312, 2022). "Then we found that overexpression of TRMT61B, TRMT6, TRMT61A, YTHDFs, ALKBH1, and ALKBH3 was significantly associated with poor overall survival in glioma." (PMID 34631793, 2021). "Kaplan–Meier survival curves showed that overexpression of TRMT61B, TRMT6, TRMT61A, YTHDFs, ALKBH1, and ALKBH3 was significantly associated with poor overall survival in glioma." (PMID 34631793, 2021). "The eraser ALKBH1 promotes cancer cell proliferation in glioma." (PMID 34631793, 2021). "Noteworthily, demethylation-inhibiting IDH1 mutation increases the DNA 6mA content in human gliomas, but the depletion of the demethylase candidate ALKBH1 fails to do so, together suggesting the presence of other unknown 6mA demethylase for erasing misincorporated DNA 6mA." (PMID 35501312, 2022). "We found that ALKBH1, TRMT6, TRMT10C, YTHDF1, and YTHDF2 were significantly overexpressed in high-grade gliomas and the expression of TRMT6 and YTHDF2 was higher in IDH wild-type patients." (PMID 34631793, 2021). "The differential analysis showed that ALKBH1, TRMT6, TRMT10C, YTHDF1, and YTHDF2 were significantly overexpressed in high-grade gliomas." (PMID 34631793, 2021).
pancreatic cancer (6 papers, 2021 to 2025). "As far as our research is concerned, the fact is that the overexpression of ALKBH1 is negatively correlated with the clinical stage of pancreatic cancer and is associated with a good prognosis." (PMID 33779693, 2021). "Notably, the expression level of ALKBH1 is closely associated with the prognosis of patients with pancreatic cancer." (PMID 35401564, 2022). "Previous studies have established a robust relationship between ALKBH1‐demethylated m1A modification and various cancers, such as pancreatic cancer and colorectal cancer." (PMID 41017026, 2025). "For example, low ALKBH1 expression is related to the poor prognosis of patients with pancreatic cancer." (PMID 36550779, 2023). "In summary, we studied the genetic changes of m1A-regulating genes in pancreatic cancer and determined the functional expression levels of the ALKBH1 gene in GSEA, which confirmed its role in cancer development." (PMID 33779693, 2021). "We also found a prognostically valuable relationship between expression of ALKBH1 and the survival time of patients with pancreatic cancer." (PMID 33779693, 2021). "This is consistent with our findings in pancreatic cancer, indicating that ALKBH1 is a potential marker for the development of disease." (PMID 33779693, 2021). "For example, in pancreatic cancer, ALKBH1 functions as a demethylase of m1A modification, participating in the occurrence and development of pancreatic cancer through the mTOR and ErbB signalling pathways, and its low expression is related to the poor prognosis of patients." (PMID 41017026, 2025). "Previous studies have shown that ALKBH1 may participate in the occurrence and development of pancreatic cancer through the mTOR and ErbB signaling pathways as an m1A regulator." (PMID 36550779, 2023). "In addition, the low expression of the ‘eraser’ gene ALKBH1 is related to the poor prognosis of patients with pancreatic cancer, and its expression level has important clinical significance for patients with pancreatic adenocarcinoma (PAAD)." (PMID 33779693, 2021). "Mechanistically, ALKBH1 may participate in the occurrence and development of pancreatic cancer through mTOR and ErbB signaling pathway." (PMID 33779693, 2021).
breast carcinoma (4 papers, 2022 to 2025). "Conversely, ALKBH1 was markedly upregulated in colorectal and breast cancers, correlating with metastasis and an unfavorable prognosis." (PMID 38317214, 2024). "With compared the expression of ALKBH family members in breast cancer and normal samples, the up-regulation was ALKBH1, ALKBH2, ALKBH4, ALKBH6, ALKBH7, and others such as ALKBH3, ALKBH8, FTO was down-regulation." (PMID 35980268, 2022). "Intriguingly, breast cancer investigations revealed a 7% genetic alteration involving ALKBH1." (PMID 38317214, 2024). "In breast cancer (BRCA), the model selected HNRNPC, IGF2BP2, IGF2BP3, FTO, METTL16, and ALKBH1." (PMID 40565233, 2025).
virus infection (4 papers, 2020 to 2023). "ALKBH1 knockdown mimicked viral infection, but caused increased viral NS3 protein levels during infection, while ALKBH1 overexpression reduced NS3 levels and viral replication, and increased f5C and f5Cm." (PMID 37986976, 2023).
colorectal cancer (3 papers, 2023 to 2025). A primary or metastatic malignant neoplasm that affects the colon or rectum. "For example, in colorectal cancer, ALKBH1‐mediated m1A demethylation of METTL3 mRNA promotes metastasis by downregulating SMAD7 expression." (PMID 41017026, 2025). "Relationship between the expression of ALKBH1 and clinicopathologic factors of colorectal cancer (CRC) patients." (PMID 36550779, 2023). "ALKBH1‐mediated m1A demethylation of METTL3 mRNA promotes the metastasis of colorectal cancer by downregulating SMAD7 expression." (PMID 36550779, 2023). "For the m1A eraser genes ALKBH1 and ALKBH3, it was suggested that the mRNA expression of MFAP2 and the methylation modification of m1A were increased in colorectal cancer when ALKBH1 was silenced." (PMID 37178414, 2023).